HSPA1B (heat shock protein family A (Hsp70) member 1B)
Diseases named in the same sentence as HSPA1B in open-access papers (continued):
Sharing a sentence is not in itself a finding about the gene and the disease.
melanoma (4 papers, 2011 to 2025). A malignant, usually aggressive tumor composed of atypical, neoplastic melanocytes. "Increased expression of HSPA1B correlates with the ability of melanoma cells to evade the immune response, leading to increased melanoma growth and poor overall survival." (PMID 39763976, 2024). "RNA sequencing data revealed high transcript levels of Hspa1a/Hspa1b, a duplicated HSP70 locus located in the class III region of the major histocompatibility complex on chromosome 6p21.3, across several melanoma cell lines." (PMID 41148289, 2025). "In a previous study we used Lipofectin for transient transfection of B16F10 mouse melanoma cells, with a construct containing a EGFP reporter gene controlled by the Hspa1b gene promoter." (PMID 21663599, 2011). "When the predictive power of all of these genes was tested on an ICI-treated melanoma patient cohort, 11 out of the 13 in vitro stable (containing IRGs SOX4, DEK, and HSPA1B) and AQP1 and CDCA4 in vivo stable DEGs were differentially expressed in the tumors of ICI responder melanoma patients." (PMID 35269844, 2022).
type 2 diabetes (4 papers, 2017 to 2024). "Additionally, HSPA1B rs2763979 showed a significant association with the risk of diabetic nephropathy in type 2 diabetes among the Indian population." (PMID 36553658, 2022).
legionellosis (3 papers, 2021 to 2025). Any disease caused by Legionella bacteria. "Hspa1b, which encodes a heat-shock protein, is involved in the upregulated KEGG pathway associated with legionellosis." (PMID 40227606, 2025). "Interfering a series of human diseases pathways including legionellosis, toxoplasmosis, and measles and some key factors such as MAFF, HSPA1A, HSPA1B, AOC1, and MX2, high doses of moxa smoke influenced the function of rat lungs." (PMID 34961819, 2021).
major depressive disorder (3 papers, 2019 to 2026). An episode of depression lasting two or more weeks without an intervening episode of mania. "The analysis of mRNA expression in the prefrontal cortex of suicide victims with major depressive disorder revealed a differential profile with 27 downregulated mRNAs, including HSPA1A, HSPA1B, DNAJB1, NR4A1, and GADD45B, which are involved in proteostasis, transcriptional regulation, and apoptosis." (PMID 41977312, 2026).
Obesity (3 papers, 2017 to 2023). Accumulation of substantial excess body fat. "It has been reported that the expression of HSPA1A/HSPA1B (HSP70/HSP 72) was decreased by obesity, insulin resistance, and ageing." (PMID 37238736, 2023).
Parkinson disease (3 papers, 2019 to 2022). A progressive degenerative disorder of the central nervous system characterized by loss of dopamine producing neurons in the substantia nigra and the presence of Lewy bodies in the substantia nigra and locus coeruleus. "Genes enriched in multiple signaling pathways, like pathways of “Heterotrimeric G-protein signaling pathway” and “B cell activation,” were altered by Hspa1b deficiency in an MPTP-induced mouse model of Parkinson disease." (PMID 31447881, 2019). "HSPA1B had been identified as one disease-relevant molecular target in advanced-stage Parkinson’s disease." (PMID 36120453, 2022).
Stroke (3 papers, 2013 to 2025). Sudden impairment of blood flow to a part of the brain due to occlusion or rupture of an artery to the brain. "In our study, HSPA1B was associated with upregulated ubiquitination, and its protection against stroke might be weakened." (PMID 37701139, 2023). "HSPA1B, which encodes heat-shock protein 70 kDa (Hsp70), protects against stroke in AF patients." (PMID 37701139, 2023). "Given that Hspa1a and Hspa1b were the most upregulated genes in the post-ischemic endfoot translatome, we asked whether their protein product, inducible HSP70, was more abundant in endfeet after stroke." (PMID 39796165, 2025).
cardiac hypertrophy (2 papers, 2019 to 2023). "Furthermore, Hsp70 (HSPA1B), for which a gene knockout has been described to induce cardiac dysfunction and development of cardiac hypertrophy, is down-regulated in both disease conditions." (PMID 36627164, 2023). "It has been shown that the Hspa1a−/−/Hspa1b−/− double knock out (KO) mice can grow to adulthood with only mild cardiac hypertrophy, indicating that HSP70 may be not essential for cell cycle progression and division during normal mouse embryo development." (PMID 31110557, 2019).
colorectal cancer (2 papers, 2022 to 2023). A primary or metastatic malignant neoplasm that affects the colon or rectum. "Increased HSPA1B expression and decreased HSPA1B promoter methylation level are both associated with a poor prognosis in colorectal cancer." (PMID 37701039, 2023).
COVID-19 (2 papers, 2023 to 2025). A disease caused by infection with severe acute respiratory syndrome coronavirus 2. "Data from the LKP indicate that the SNP rs6457452 HSPA1B increases the risk of hospitalization with COVID-19 and exacerbates the severity of its course." (PMID 41009536, 2025). "We found that the risk allele T rs6457452 HSPA1B is associated with an increased risk of severe COVID-19 in patients aged 68 years or older as well as in patients with low physical activity." (PMID 41009536, 2025). "According to the Lung Disease Knowledge Portal bioinformatic resource, first, rs910652 HSPA12B was linked to a lower risk of very severe respiratory confirmed COVID-19 cases, whereas rs6457452 HSPA1B was associated with an increase in hospitalization due to COVID-19." (PMID 41009536, 2025). "Specifically, the polymorphic variants rs1136141 and rs1461496 HSPA8, rs1042665 HSPA9, rs7189628 DNAJA2, rs910652 HSPA12B, rs6457452 HSPA1B and rs1043618 HSPA1A are associated with alerted risk of severe COVID-19." (PMID 41009536, 2025). "Notably, two SNPs rs1136141 HSPA8 and rs7189628 DNAJA2 are associated with severe COVID-19 in patients under 68 years of age, whereas in older patients, SNPs rs1461496 HSPA8, rs910652 HSPA12B, rs1043618 HSPA1A and rs6457452 HSPA1B are significantly associated with severe disease." (PMID 41009536, 2025).
diabetic foot ulcers (2 papers, 2022 to 2023). "Polymorphisms in the HSPA1B gene have been found to be associated with the severity of diabetic foot ulceration and chronic heart failure." (PMID 37569434, 2023).
diabetic nephropathy (2 papers, 2022). "HSPA1B polymorphisms have also been reported to be associated with coronary artery disease, multiple sclerosis and diabetic nephropathy." (PMID 36291674, 2022).
erythroleukemia (2 papers, 2024 to 2025). Acute erythroid leukemia characterised by the presence of at least 50% erythroid precursors and at least 20% myeloblasts in the bone marrow. "HSPA1B was induced in the in erythroleukemia cells and knockdown of HSPA1B accelerated leukemic cell proliferation." (PMID 40822462, 2025).
glaucoma (2 papers, 2019 to 2021). Increased pressure in the eyeball due to obstruction of the outflow of aqueous humor. "A recent pathway analysis of GWAS data revealed an association of several histocompatibility (MHC) subtypes along with Ctss and heat shock protein (HSP) 70, HSPA1B, with primary open angle glaucoma." (PMID 34299211, 2021). "Furthermore, some previous identified glaucoma autoantigens including heat shock protein 60 dDA (HSPD1), heat shock protein 70 kDa (HSPA1B), vimentin (VIM), α-enolase (ENO1) and superoxide dismutase 1 (SOD1) could be detected." (PMID 30899261, 2019).
Hearing impairment (2 papers, 2017 to 2021). A decreased magnitude of the sensory perception of sound. "Different haplotypes of HSPA1L/HSPA1A/HSPA1B SNP combinations were associated with variable etiologies of hearing impairment." (PMID 33926545, 2021). "Some studies analyzed the associations of HSPA1B SNP rs2763979 with certain diseases other than hearing impairments." (PMID 33926545, 2021). "In our earlier studies on the associations of HSP70 genetic polymorphisms (HSPA1L/HSPA1A/HSPA1B: rs2075800/rs1043618/rs2763979) with NIHL and sudden sensorineural hearing loss (SSNHL), different haplotypes were associated with diverse risks of these hearing impairments." (PMID 33926545, 2021).
heart failure (2 papers, 2016 to 2024). Inability of the heart to pump blood at an adequate rate to meet tissue metabolic requirements. "Additionally, various medications have been identified that can indirectly influence HSPA1B expression and activity, showing efficacy in heart failure and related diseases." (PMID 39512814, 2024).
Insulin resistance (2 papers, 2022 to 2023). Increased resistance towards insulin, that is, diminished effectiveness of insulin in reducing blood glucose levels. "HSPA1B mRNA showed a significant difference in its expression regarding the insulin resistance." (PMID 36139069, 2022).
ischemia (2 papers, 2021 to 2024). A hypoperfusion of the BLOOD through an organ or tissue caused by a PATHOLOGIC CONSTRICTION or obstruction of its BLOOD VESSELS, or an absence of BLOOD CIRCULATION. "The HSPA1B gene, also known as heat shock 70 kDa protein 1B encodes a 70 kDa heat shock protein (Hsp), a member of the heat shock protein 70 family, is known to be induced by ischemia, reperfusion and surgical stress." (PMID 33467096, 2021). "Research indicates that higher levels of HSPA1B can notably decrease myocardial cell death during ischemia-reperfusion injury." (PMID 39512814, 2024).
ischemic stroke (2 papers, 2015 to 2023). A stroke disorder caused by obstruction of blood flow to the brain, due to thrombotic (local blood clot formation) or embolic (due to a blood clot or other material traveling from another site) event. "Among the upregulated genes, Hspa1b, Ccl2, Cxcl2, Ccl3, Serpina3n, Timp1, H19, Hspb1, Ccl20, and Cxcl1 were found to demonstrate significant upregulation in pathological phase of ischemic stroke." (PMID 25861363, 2015).
malaria (2 papers, 2015 to 2024). Malaria is a serious and sometimes fatal disease caused by a parasite that commonly infects a certain type of mosquito which feeds on humans. "Whereas the rs6457452 SNP (HSPA1B) was associated with 34% reduced risk of severe malarial anemia (OR for additive T allele, 0.661; P = .0073), there was weaker evidence for an effect on severe malaria overall (P = .010)." (PMID 25805752, 2015). "Of relevance to the role of HSPs in human malaria pathogenesis, transcripts for HSP60 (HSPD1) were down-regulated in SMA (log2FC = −0.81), as were HSP70 family members: HSPA1A (−1.31), HSPA1B (−0.99), HSPA4 (−0.33), HSPA4L (−0.68), HSPA5 (−0.51), and HSPA6 (−0.81)." (PMID 39452740, 2024).
multiple sclerosis (2 papers, 2022). A progressive autoimmune disorder affecting the central nervous system resulting in demyelination. "The HSPA1B rs1061581 polymorphism (1267 A/G), which is linked to the risk of developing multiple sclerosis, is related to ROS levels and has a role in the variation in HSPA1B expression levels under oxidative stimulus." (PMID 35269451, 2022).
ovarian carcinoma (2 papers, 2021 to 2025). A malignant neoplasm originating from the surface ovarian epithelium. "We also observed downregulation of key HSPs including Hspa1a, Hspa1b, and Dnajb1 upon Ier5 knockdown in HM-1 and MOV ovarian cancer cells." (PMID 40002205, 2025). "Our results show that ADIRF, SLC2A5, C3orf86, HSPA1B are among the most significant PCa biomarkers, while MTRNR2L1, EEPD1, TEPP and VN1R2 are jointly important biomarkers across prostate, breast and ovarian cancers." (PMID 34001952, 2021).
prostate carcinoma (2 papers, 2024). A carcinoma that arises from epithelial cells of the prostate gland. "IPA® projected the association of several proteins’ downregulation, including heat shock protein families α and β (HSPA1A/HSPA1B) and peptidylprolyl isomerase A (PPIA), with prostate cancer apoptosis." (PMID 39598420, 2024).
respiratory failure (2 papers, 2020 to 2025). The significant impairment of gas exchange within the lungs resulting in hypoxia, hypercarbia, or both, to the extent that organ tissue perfusion is severely compromised. "Regarding the associations between HSPs SNPs and respiratory failure indicators, we found that rs6457452 HSPA1B (p = 0.03) and rs753856 HSPA6 (p = 0.02) were linked to prolonged oxygen therapy, whereas rs706121 BAG1 (p = 0.04) decreased the duration of lug ventilation, indicating a better prognosis." (PMID 41009536, 2025). "Elevated protein chaperones Hspa1a and Hspa1b in medulla during SA may reflect a seasonal remodeling of electrophysiological properties to protect against respiratory failure at low temperatures, as shown for hamsters prior to hibernation." (PMID 33536943, 2020).
Sepsis (2 papers, 2016 to 2020). Sepsis is defined as life-threatening organ dysfunction caused by a dysregulated host response to infection. "In rats, raloxifene prevents severe sepsis through induction of HSPA1B with an anti-inflammatory effect." (PMID 32174955, 2020). "Research on different phases of sepsis found that HSPA1B can be considered a serum marker for the acute proinflammatory phase." (PMID 32174955, 2020). "Study on Multiple organ dysfunction syndrome in sepsis found that increased HSPA1B has an anti-inflammatory effect." (PMID 32174955, 2020). "There is evidence that heat stress induces HSPA1B to prevent lethal sepsis." (PMID 32174955, 2020). "Hesperidin can protect against lung injury induced by sepsis, also through induction of HSPA1B." (PMID 32174955, 2020). "Results showed that TNF, HSPA1A, HSPA1B, TREM1, SOD2 and MIF genes related to sepsis correspond to m6A-cis-eQTLs." (PMID 32174955, 2020). "HSPA1B, with 61 m6A-cis-eQTLs, also named HSP70, is involved in the inflammatory response, which is an important biological step in the development of sepsis." (PMID 32174955, 2020).
toxoplasmosis (2 papers, 2021 to 2025). A parasitic disease contracted by the ingestion or fetal transmission of toxoplasma gondii. "Decreased levels of A0A0G2JIW1 (HSPA1B) and A0A384P5Q0 (catalase) along with enriched KEGG pathways including “longevity regulating pathway - multiple species,” “influenza A,” “glyoxylate and dicarboxylate metabolism,” and “toxoplasmosis” suggest vulnerabilities to aging and oxidative stress." (PMID 39562369, 2025).
acute myeloid leukemia (1 paper, 2024). Acute myeloid leukemia (AML) is a group of neoplasms arising from precursor cells committed to the myeloid cell-line differentiation. "There is a close relationship between UNC93B1, IL2RA, HSPA1B, and SOCS1 overexpression and chemotherapy resistance in patients with acute myeloid leukemia (AML)." (PMID 39213256, 2024).
acute myocardial infarction (1 paper, 2022). Necrosis of the myocardium, as a result of interruption of the blood supply to the area. "For example, HSPA1B is a subtype of heat shock protein 70 that up-regulated in mice with global ischemia and in mice with acute myocardial infarction." (PMID 36743288, 2022).
acute renal failure (1 paper, 2022). "In developmental studies, it was found that in very low birth weight neonates, the HSPA1B GG genotype was associated with low HSP 72 (HSPA1B) expression and was also associated with the risk of premature birth and acute renal failure." (PMID 36291674, 2022).
amyloidosis (1 paper, 2022). A disorder characterized by the localized or diffuse accumulation of amyloid protein in various anatomic sites. "However, our data showed that IT and amyloidosis induced upregulation of Hspb1 and HSPB1 in the liver and spleen but did not increase other common HSPs, such as Hsp70/Hspa1b and Cryab (also known as Hspb5)." (PMID 35099007, 2022).
anaplastic carcinoma (1 paper, 2022). "Based on differentially expressed genes derived from the subclusters, gene set enrichment analysis showed that EC (ATP1B3) and EC (HSPA1B) contribute to the process of metastasis, for example, in fibrosarcoma and anaplastic carcinoma." (PMID 35265720, 2022).
asthma (1 paper, 2022). "This study unequivocally reported that HSPA1B rs2763979 was associated with asthma prognosis regarding favorable pulmonary function parameters." (PMID 36553658, 2022). "Overall analysis showed that the HSPA1B rs2763979 variant conferred a risk of asthma under codominant, dominant, overdominant, and log-additive models." (PMID 36553658, 2022). "In this sense, this study aimed to unravel the association of the HSPA1B rs2763979 variant with asthma susceptibility and disease characteristics." (PMID 36553658, 2022). "In conclusion, the HSPA1B rs2763979 variant might have prognostic utility as a genetic marker for asthma in our population." (PMID 36553658, 2022). "Therefore, this work was conducted to assess the association of the HSPA1B rs2763979 variant with the risk of asthma and disease characteristics aiming at prognostic assessment." (PMID 36553658, 2022). "Although the current study was the first to address the relationship of HSPA1B rs2763979 with asthma, some limitations should be considered: First, the sample was relatively small-sized." (PMID 36553658, 2022). "The HSPA1B rs2763979 variant has been associated with multiple inflammatory scenarios, but no previous studies have explored its association with asthma." (PMID 36553658, 2022). "The HSPA1B rs2763979 variant (c.+1538A>G) is located on Chr6: 31,826,815 (on Assembly GRCh38) and has been associated with chronic obstructive lung diseases and lung cancer, but no previous studies have explored its association with asthma in particular in the Middle East population." (PMID 36553658, 2022).
atrial fibrillation (1 paper, 2023). A disorder characterized by an electrocardiographic finding of a supraventricular arrhythmia characterized by the replacement of consistent P waves by rapid oscillations or fibrillatory waves that vary in size, shape and timing and are accompanied by an irregular ventricular response. "These genes include heat shock proteins Hspa1a and Hspa1b which serve as chaperones for other proteins involved in cytoskeleton function and have been associated with atrial fibrillation and colorectal polyp formation." (PMID 37113661, 2023).
autoimmune disease (1 paper, 2024). A disorder resulting from loss of function or tissue destruction of an organ or multiple organs, arising from humoral or cellular immune responses of the individual to their own tissue constituents. "Then, we performed mediation analyses, which showed that POR, HSPA1B, SHANK3, and BRD2 might exert mediating effects from air pollutants to increased risk of autoimmune diseases." (PMID 38685026, 2024). "Furthermore, intermediate analyses revealed that air pollutants increased the risk of autoimmune diseases by modulating the expression of POR, HSPA1B, SHANK3, and BRD2." (PMID 38685026, 2024). "Two-step MR revealed that POR, HSPA1B, and BRD2 might mediate from air pollutants to autoimmune diseases." (PMID 38685026, 2024).
bladder cancers (1 paper, 2013). "The importance of maintaining Hsp72 protein levels is highlighted by our discovery of dramatic compensatory upregulation of the HSPA1B isoform in bladder cancer cells that lack the A1A isoform." (PMID 23874968, 2013). "Together, our results provide proof-of-concept for using Hsp72 inhibitors to promote bortezomib sensitivity in bladder cancers and suggest that selective targeting of HSPA1B could produce synthetic lethality in tumors that display HSPA1A promoter methylation." (PMID 23874968, 2013). "Developing strategies to specifically inhibit HSPA1B could produce synthetic lethality in bladder cancers and other tumors with HSPA1A methylation." (PMID 23874968, 2013).
breast invasive carcinoma (1 paper, 2025). "According to the GEPIA2 database, both HSPA1A and HSPA1B are significantly highly expressed in breast invasive carcinoma (BRCA) compared to healthy tissue." (PMID 40426862, 2025).